ANXA1 (annexin A1)
Diseases named in the same sentence as ANXA1 in open-access papers (continued):
Sharing a sentence is not in itself a finding about the gene and the disease.
Arthritis (23 papers, 2009 to 2025). Inflammation of a joint. "In models of contact hypersensitivity, collagen‐induced arthritis and inflammation induced by transgenic T cells, deficiency of ANXA1 was associated with exacerbated inflammation." (PMID 35146757, 2022). "In particular, loss of ANXA1 in a model of arthritis was associated with increased antigen‐specific T‐cell activation." (PMID 35146757, 2022). "Having established this clinically relevant model of diastolic dysfunction associated with arthritis, we then investigated the potential beneficial effects of human recombinant AnxA1 (hrAnxA1) against the diastolic dysfunction of K/BxN F1 mice." (PMID 34526398, 2021). "AnxA1-KO mice demonstrate a prolonged and amplified inflammatory response after local stimulation (e.g., paw edema model), an increased extent of joint damage in the antigen-induced arthritis model and a greater susceptibility to nociception." (PMID 37190040, 2023). "AnxA1 is produced in response to glucocorticoids, and reduced AnxA1 levels have recently been associated with CHIKV-induced arthritis and may be a biomarker for determining the severity of the disease." (PMID 37190040, 2023). "The pro-resolving protein annexin A1 (AnxA1) was also described as a potential effector of EV in arthritis." (PMID 40943586, 2025). "Neutrophils recruited to the joint during an arthritis flare-up release high numbers of EVs, which are able to successfully penetrate cartilage and deliver AnxA1 to the chondrocytes through the extracellular matrix." (PMID 36291183, 2022). "Using ALX/FPR2, AnxA1 functions to resolve diverse inflammatory events, including reduction of joint injury in experimental arthritis, lessening of salivary gland inflammation, and contributes to corneal wound healing." (PMID 33968020, 2021). "The role of AnxA1 in experimental arthritis has been reported with different outcomes depending on the model and the route of administration." (PMID 34526398, 2021). "In the antigen-induced arthritis model, the Met-BSA induced arthritis through a Th2-response, demonstrating a protective AnxA1 role in RA." (PMID 34220836, 2021). "ANXA1 knock out mice are resistant to the effects of glucocorticoids in a model of amatory arthritis of suggesting that ANXA1 is one of the main anti-inflammatory effector molecules of glucocorticoids." (PMID 31114582, 2019). "Deletion of annexin A1 (an endogenous FPR2 agonist) has been shown to exacerbate arthritis severity in the K/BxN serum-injected mice, suggesting a crucial role of annexin A1 in the regulation of RA pathogenesis." (PMID 30279454, 2018). "Annexin A1−/− mice, for example, develop more severe inflammatory lesions of cartilages in experimental models of arthritis." (PMID 29751523, 2018). "Administration of human recombinant AnxA1 during the immunization phase of the collagen-induced arthritis model exacerbates signs and symptoms of diseases." (PMID 19912648, 2009). "Thus, AnxA1 plays an important role in chronic inflammatory disorders such as arthritis and chronic obstructive pulmonary disease." (PMID 36766501, 2023). "This suggests that targeting the AnxA1/FPR2 pathway might be beneficial in managing Chikungunya fever (CHIKF) and its associated arthritis." (PMID 37190040, 2023). "In contrast, injection with exogenous ANXA1 exacerbated the severity of arthritis in CIA mice." (PMID 33473125, 2021). "Future experimental studies are warranted to investigate whether AnxA1 or other specific pro-resolving mediators are cardioprotective in experimental models of arthritis." (PMID 33924323, 2021). "AnxA1 serves as an important anti-inflammatory regulatory factor in various animal models of inflammatory diseases, including multiple sclerosis, peritonitis, arthritis, and various types of IR injury." (PMID 33796096, 2021). "These experiments showed that AnxA1 could increase arthritis symptoms if administered during the immunization phase of the CIA." (PMID 34220836, 2021).
Arthritis (continued). "However, human annexin A1 has been reported to induce increased clinical signs of RA in the collagen-induced arthritis model by modulating T cell differentiation." (PMID 30279454, 2018). "Similar to the arthritis study, the absence of AnxA1 was associated with evidence of increased allergic inflammation in the OVA-challenged lung, including increased eosinophil recruitment, IL-4 production, and airways dysfunction." (PMID 23230437, 2012). "In fact, the ability of AnxA1 to stimulate endogenous pro-resolving pathways leading to tissue repair and healing and its therapeutic effects have been documented in a broad range of experimental models, including myocardial ischemia injury, stroke, sepsis, arthritis, and multiple sclerosis." (PMID 35798730, 2022). "The functional role of FPR2 in the regulation of RA pathogenesis was also demonstrated by showing that deletion of annexin A1, an endogenous FPR2 agonist, exacerbates arthritis severity in K/BxN serum‐injected mice." (PMID 34378309, 2021). "Furthermore, the absence of AnxA1 has recently been reported to be without effect in a T cell-independent, antibody transfer model of arthritis, indicating that under some conditions, the role of AnxA1 is minimal." (PMID 23230437, 2012). "Our experience with the serum-transfer model of arthritis did not highlight powerful inhibitory properties of hrAnxA1 on joint inflammation, but 1) a cleavage-resistant AnxA1 was effective in attenuating joint disease, and 2) dexamethasone lost most of its efficacy in AnxA1 null mice." (PMID 34526398, 2021).
nasopharyngeal carcinoma (22 papers, 2015 to 2025). A carcinoma arising from the nasopharyngeal epithelium. "In a mouse model for multiple myeloma, AnxA1 depletion improved bortezomib treatment, but in nasopharyngeal carcinoma xenografts, loss of AnxA1 enhanced radiotherapy resistance." (PMID 33810523, 2021). "This may be a direct cause of the decline in ANXA1 expression in nasopharyngeal carcinoma, accelerating lymph node metastasis in nasopharyngeal carcinoma." (PMID 40551992, 2025). "Compared with the control group, the methylation level of the ANXA1 gene in nasopharyngeal carcinoma tissues was extremely high, reaching 92%." (PMID 40551992, 2025). "In nasopharyngeal carcinoma, decreased ANXA1 leads to the upregulation of S100A9/vimentin, which increases tumour invasion by regulating the function of the cytoskeletal proteins." (PMID 36936694, 2023). "A study showed that the inhibition of ANXA1 in nasopharyngeal carcinoma increased the trauma-healing ability of the cells, and the activation of the ANXA1 gene decreased the trauma-healing rate by 70%." (PMID 36936694, 2023). "ANXA1 was confirmed to participate in regulatory T cell (Treg)-mediated immune suppression in triple-negative breast cancer and can promote nasopharyngeal carcinoma growth and metastasis." (PMID 34150627, 2021). "Our previous studies have shown that the abnormal expression of Annexin A1 is related to the occurrence and development of nasopharyngeal carcinoma (NPC)." (PMID 28355254, 2017). "In addition, ANXA1 contributes to tumor cell migration and dissemination by autophagy inhibition in nasopharyngeal carcinoma." (PMID 41283264, 2025). "Accordingly, inhibition of the c-Cbl-EphA2 interaction, due to molecular competitors such as the Ca2+ or phospholipid-binding protein Annexin A1 (ANXA1), increases EphA2 protein stability and promotes nasopharyngeal carcinoma in vitro and in vivo growth and metastasis." (PMID 39596256, 2024). "ANXA1 also binds and stabilizes EphA2 to promote nasopharyngeal carcinoma growth and metastasis." (PMID 36678567, 2023). "In contrast, ANXA1 shows low expression levels in thyroid cancer and nasopharyngeal carcinoma." (PMID 36988561, 2023). "However, experiments performed in nasopharyngeal carcinoma cells, suggest that knockdown of ANXA1 inhibits DNA damage by decreasing the generation of intracellular reactive oxygen species and the formation of γ-H2AX and promotes DNA repair by increasing DNA-dependent protein kinase activity." (PMID 37373303, 2023). "Additionally, ANXA1 targeting could be useful, considering that it promotes the progression and metastasis of nasopharyngeal carcinoma through the stabilization of ephrin type-A receptor 2 (EphA2), and that exosomal ANXA1 is driving the malignant transformation of thyroid cells in thyroid cancer." (PMID 41283264, 2025). "ANXA1 inhibits cellular autophagy and promotes tumour invasion and metastasis through PI3K/AKT signalling activation in nasopharyngeal carcinoma." (PMID 36936694, 2023). "Others have reported markedly reduced staining for Annexin-A1 in tissue specimens diagnosed with nasopharyngeal carcinoma compared to noncancerous mucosa of same site." (PMID 37954869, 2023).
Obesity (22 papers, 2013 to 2026). Accumulation of substantial excess body fat. "Previous data has shown that ANXA1 is associated with β-cell function as well as glucose homeostasis and higher circulating levels are reported in type 2 diabetes-related obesity." (PMID 39432712, 2024). "To further elucidate the association between the increased adipose tissue ANXA1 levels and obesity, we examined metabolic function in a systemic ANXA1 overexpression mouse model (Anxa1Tg), generated by targeted transgenesis." (PMID 39174522, 2024). "The aim of the current study was to investigate the role of annexin A1 in obesity and associated inflammation." (PMID 35684160, 2022). "In obese mouse adipose tissue Anxa1, which encodes the phospholipid‐binding protein annexin A1, was the most highly expressed ligand mRNA, and its expression increased in obesity to 329 ± 54% of the levels quantified in adipose tissue from lean mice." (PMID 36245259, 2022). "Based on our initial observations, the aim of the current study was to further investigate the role of ANXA1 in obesity and its associated inflammation." (PMID 35684160, 2022). "The aim of the current study was to investigate the role of ANXA1 in obesity and associated inflammation using relevant human and cell culture models." (PMID 35684160, 2022). "The exacerbation of obesity-associated metabolic diseases in AnxA1 null mice was confirmed in a further study." (PMID 31337068, 2019). "In summary, obesity in mice is associated with upregulated expression of ANXA1 in adipose tissue and this occurs in a leptin- and IL-6-independent fashion." (PMID 24312665, 2013). "Overall, these data demonstrate that ANXA1 deficiency leads to increased adiposity in response to HFD in an obesity-resistant background." (PMID 24312665, 2013). "However, the effects of ANXA1 or its associated peptides in obesity-associated inflammation are limited." (PMID 35684160, 2022). "Interestingly, the relationship between AnxA1, obesity, and obese-associated metabolic diseases has been well documented due to the role of AnxA1 in the treatment of type-2 diabetes." (PMID 33213098, 2020). "Although AnxA1 up-regulation paralleled the severity of NASH, an increased expression of AnxA1 was already evident along with early signs of inflammation in livers with only steatosis induced by feeding mice for 12 weeks with an HFD that caused obesity and IR." (PMID 24668763, 2014). "Because obesity is often associated with altered glucose metabolism, we next investigated whether ANXA1 deficiency affects glycemic control." (PMID 24312665, 2013). "However, the specific effects of ANXA1 in obesity and the underlying mechanisms of action remain unclear." (PMID 39174522, 2024). "Peripherally, ANXA1 may act in an endocrine manner to regulate inflammatory biomarkers to dampen inflammation, regulate insulin secretion and improve the metabolic profile to reduce the risk of developing obesity associated co-morbidities." (PMID 35684160, 2022). "Therefore, evaluating the effect of ANXA1 deficiency in VAT inflammation in an obesity-prone strain may generate more conclusive results of the functional association between ANXA1 and metabolic inflammation." (PMID 24312665, 2013). "In the present study we investigated the modulation of ANXA1 in adipose tissue in models of diet-induced (DIO) and genetic obesity, and also studied whether ANXA1 participates in modulation of adiposity, glucose metabolism and obesity-associated inflammation using a model of DIO." (PMID 24312665, 2013). "Global knockout of ANXA1 followed by an HFD in C57BL/6 mice aggravates obesity and insulin resistance." (PMID 39174522, 2024). "Firstly, our study reveals for the first time the pathway via which ANXA1 prevents obesity by inhibiting adipogenesis in mice." (PMID 39174522, 2024). "In conclusion, the molecular mechanism of ANXA1 inhibiting adipogenesis was first uncovered in our study, which is a potential target for obesity prevention and treatment." (PMID 39174522, 2024).
Obesity (continued). "Treatment with Ac2-26, an active peptide derived from ANXA1, inhibits both adipogenesis and obesity through the mechanism." (PMID 39174522, 2024). "Herein, we focused on purified preadipocytes and have elucidated the anti-obesity role of ANXA1, PDLIM7 and MYCBP2 in the suppression of adipogenesis, along with the underlying molecular mechanisms." (PMID 39174522, 2024). "The findings indicated a correlation between the elevated adipose tissue ANXA1 levels and obesity in humans and mice." (PMID 39174522, 2024). "Mice with adipose tissue-specific knockout of ANXA1 exhibit exacerbated obesity and metabolic disorders after HFD." (PMID 39174522, 2024). "In contrast, the global overexpression of ANXA1 effectively prevents HFD-induced obesity and metabolic dysfunction in mice." (PMID 39174522, 2024). "Correspondingly, we set forth to better understand the role of ANXA1 in adipose tissue than in other tissues in obesity." (PMID 39174522, 2024). "The data demonstrate that the knockout of ANXA1 promotes HFD-induced obesity and metabolic disorders in mice, and underscore the critical contribution of ANXA1 in the development of obesity." (PMID 39174522, 2024). "Our study reveals molecular mechanisms linking ANXA1 to adipose tissue homeostasis and obesity for the first time, and provides insights for potential interventions in metabolic disorders." (PMID 39174522, 2024). "It is of interest for future studies to investigate the effects of systemic inflammation on the expression and regulation of ANXA1 in obesity." (PMID 35684160, 2022). "The roles of annexin A1 were explored using an in vitro cell based model (SGBS cells) mimicking the inflammatory status that is observed in obesity." (PMID 35684160, 2022). "Taken together, most of the data summarized above point towards disease-preventing activities of AnxA1 in obesity." (PMID 31337068, 2019). "Further documenting a relationship between AnxA1 and obesity, AnxA1 mRNA was strongly increased in adipose tissue of mice on a high fat diet." (PMID 31337068, 2019). "To elucidate the role of ANXA1 in the pathophysiology of obesity/metabolic syndrome, we used a model of HFD-induced insulin resistance in WT and ANXA1−/− mice." (PMID 30972066, 2019). "Recent studies suggest that the AnxA1/FPR2 axis is highly relevant for obesity and related inflammation, as well as other complications, such as insulin resistance, T2D and atherosclerosis." (PMID 31337068, 2019). "Because changes in AnxA1 expression within adipose tissue characterize obesity in mice and humans, we queried a possible role for AnxA1 in the pathogenesis of nonalcoholic steatohepatitis (NASH), a disease commonly associated with obesity." (PMID 24668763, 2014). "In agreement, we show that HFD-induced upregulation of ANXA1 expression was much more pronounced in adipose tissue of obesity-prone C57BL6 mice compared to Balb/c mice." (PMID 24312665, 2013). "Transcriptome analysis of human adipose tissue reveals increased ANXA1 expression in response to obesity." (PMID 24312665, 2013). "It is possible that ANXA1 is sequestered inside the expanding adipose tissue in obesity, preventing its release into the circulation." (PMID 24312665, 2013). "The objective of this study was to investigate modulation of ANXA1 in adipose tissue in murine models of obesity and to study the involvement of ANXA1 in diet-induced obesity in mice." (PMID 24312665, 2013). "The data suggest that GW9662 prevents obesity induced by Adipose tissue-specific ANXA1 KO." (PMID 39174522, 2024). "In conclusion, our study uncovers that ANXA1 prevents obesity and reduces insulin resistance." (PMID 39174522, 2024). "Next, we investigate how ANXA1 contributes to obesity in SVFs from adipose tissue." (PMID 39174522, 2024). "Whole-body or adipocyte-specific ANXA1 deletion aggravates obesity and metabolic disorders." (PMID 39174522, 2024). "Our study reveals that ANXA1 levels are elevated in the adipose tissue of individuals with obesity." (PMID 39174522, 2024).